MTOR (mechanistic target of rapamycin kinase)
Diseases named in the same sentence as MTOR in open-access papers (continued):
Sharing a sentence is not in itself a finding about the gene and the disease.
cancer (continued). "Multiple recent studies have identified mEAK-7 as a positive activator of mTOR (mammalian/mechanistic target of rapamycin) signaling via an alternative mTOR complex, implying that mEAK-7 plays an important role in the promotion of cancer proliferation and migration." (PMID 38532930, 2024). "In addition, autophagy-related signalling pathways, particularly the PI3K/AKT/mTOR pathways, are upregulated in advanced cancer stages, and the malignant phenotype of the disease reduces autophagy, leading to tumour progression." (PMID 38243224, 2024). "However, most studies showing phenothiazine induced mTOR inhibition and cancer cell cytotoxicity have used high drug doses in the range of 20-50 μM and beyond." (PMID 38177535, 2024). "However, in the case of GBM, continuous activation of the PI3K/AKT/mTOR signaling pathway occurs due to mutations in the EGFR or PTEN, leading to carcinogenesis and resistance to cancer therapy." (PMID 38686058, 2024). "Consequently, targeting the Akt-mTOR pathway has emerged as a potential therapeutic strategy against this challenging cancer, with ongoing research focused on developing inhibitors/antibodies and combination therapies to improve treatment outcomes for OS." (PMID 38228583, 2024). "The PI3K/AKT/mTOR cascade is another central signaling network that, when aberrant, leads to enhanced cellular growth, survival, and metabolism, thus providing a proliferative advantage to cancer cells." (PMID 39370455, 2024). "Additionally, we discuss a new concept for anti-cancer drug development aimed at overcoming existing drawbacks, such as drug resistance, by targeting CSCs through mTOR inhibition." (PMID 39349424, 2024). "As PTEN and mTOR are involved in cellular energy metabolism, combined with the results of our bioinformatics analyses, we conjectured that metformin may exert its cancer-suppressing effects by regulating glucose metabolism." (PMID 38811809, 2024). "Aside from folates, in vitro, glutamates released from gamma-polyglutamated -folates by PSMA have proven responsible for the activation of the P13K-Akt-mTOR pathway, known to play an important role in cancer cell survival, angiogenesis, and metastasis via the metabotropic glutamate receptor." (PMID 39273701, 2024). "In an experimental model, NF-κB and mTOR coordinated radiation-induced CXCL8 secretion in cancer cells with senescence characteristics, leading to targeted migration of CD56-dim NK cells, thus linking senescence-associated CXCL8 release to innate immune surveillance of human tumors." (PMID 38421832, 2024). "The experiments aimed at combination of the mTOR inhibition and ER stress induction followed by the mathematical modeling of cell effects observed revealed the interconnections between UPR and mTOR, which defined the dynamics of autophagy and apoptosis activation in cancer cells." (PMID 38418814, 2024). "The mTOR pathway is heavily involved in tumorigenesis and progression in various cancers." (PMID 38217303, 2024). "In the future, the design and synthesis of new and specific inhibitors of the mTOR pathway or mTOR-related pathways may eliminate cancer cells alone or in combination with chemotherapy drugs and immunotherapeutic agents." (PMID 39410026, 2024). "Thus, the effectiveness of mTOR inhibitors in cancer therapy can be evaluated by their ability to suppress both complexes along with their degree of interference in both cellular proliferation and migration." (PMID 38474373, 2024). "Additionally, evidence on kidney transplant patients found that using mTOR inhibitors protects de novo cancer formation, preventing up to half of the expected incidence of cancers." (PMID 38976168, 2024). "Autophagy-related genes may be potential drug targets via involvement in apoptosis regulation and PI3K/MTOR signaling pathways, implying their potential clinical application in cancer treatment." (PMID 38338839, 2024).
cancer (continued). "Combining lysosome-dispersing amino acids with mTOR-activating amino acids synergistically enhances mTOR activation, which may be particularly relevant in cancer cells." (PMID 39416115, 2024). "Additionally, cancer cells can activate compensatory survival pathways like the PI3K/AKT/mTOR pathway or the NF‐κB pathway to counteract the effects of cell death‐targeting therapies." (PMID 39239068, 2024). "As a result, inhibiting the PI3K/Akt/mTOR pathway is considered a potentially attractive treatment for cancer cells as reported when the following compounds were isolated: tanshinone I (from Salvia miltiorrhiza), lanatoside C, isoorientin, mahanine, piperlongumine, and apigetrin." (PMID 38527038, 2024). "For this reason, mTOR inhibitors have being investigated as potential cancer treatments." (PMID 39728071, 2024). "In addition, excessive nutrient intake promotes mTOR signaling, which in turn leads to kidney disease and cancer." (PMID 38365306, 2024). "Notably, ROS activates the PI3K/AKT/mTOR pathway, which contributes to the excessive proliferation of cancer cells." (PMID 38898042, 2024). "Understanding the specific miRNAs that target mTOR and their impact on radiosensitivity may provide new avenues for personalized cancer treatment approaches that can optimize the use of RT in individual patients." (PMID 38965615, 2024). "Moreover, it effectively inhibited the overactivation of the PI3K/Akt/mTOR pathway that has been observed because of imatinib treatment and, thus, sensitized cancer cells to the cytotoxic effects of the latter." (PMID 38672636, 2024). "Notably, cancer cells with NOP14 high expression exhibit increased sensitivity to mTOR inhibitors, because the feedback activation of the PI3K-PDK1-Akt axis by mTORC1 inhibition was compensated by mTORC2 inhibition partly through NOP14 downregulation." (PMID 38272224, 2024). "Autophagy is induced by the downregulation of the AKT and mTOR pathways in cancer cells." (PMID 39104398, 2024). "Given the role of NOP14 in mTORC2 activation, we then sought to determine whether NOP14 levels could serve as an indicator of the responsiveness to PI3K/mTOR inhibitors in cancer cells." (PMID 38272224, 2024). "Despite their limitations, mammalian target of rapamycin (mTOR) inhibitors may exhibit potential anti-tumor effects by inhibiting cancer growth through cell-cycle arrest and initiation of apoptosis." (PMID 38610636, 2024). "Similarly, cancer cells use upregulation strategies involving the mTOR signaling pathway as compensatory mechanisms." (PMID 38172946, 2024). "We investigated whether mTOR signaling plays a similar role in cancer cells undergoing VCP inhibition-induced paraptosis." (PMID 38218922, 2024). "By modulating the AKT/mTOR pathway, arbutin may promote programmed cell death in cancer cells, thereby inhibiting tumor growth." (PMID 39628695, 2024). "Furthermore, treatments that inhibit mTOR have proven effective in treating B-cell malignancies, highlighting the pivotal role of this pathway in cancer cell survival." (PMID 39186541, 2024). "Although PI3K–Akt–mTOR signaling inhibitors have theoretical potential to markedly suppress mutated cancer cells, challenges arise from negative feedback release and detrimental impacts on non-tumor cells." (PMID 39394200, 2024). "SLC36A1 activity activates mTOR and cancer cell proliferation." (PMID 39852119, 2024). "In vitro studies with PFOA exposure in a uterine cell line showed that PFOA treatment promoted invasion and migration of cancer cells mediated through activation of ERK/mTOR signaling, which cross talks to the MAPK pathway, another potential upstream mediator of paxillin." (PMID 38535903, 2024).
cancer (continued). "These dynamics may indicate decreased plasticity of tumor cells in 14-60-4 spheroids, accompanied by simultaneous activation of the PI3K/AKT/mTOR pathway, a major survival pathway activated in cancer." (PMID 38672482, 2024). "PI3K, AKT, and mTOR regulate each other to drive the development of cancer." (PMID 39366930, 2024). "We have conjugated the a-strand to carry the PI3K/mTOR inhibitor, PI-103; the b-strand to carry a fluorescent probe for detection of nanoparticle binding to cancer cell surface receptors; and c-strand to carry folate for specific binding to cancer cells FRα." (PMID 40115434, 2024). "We envision that conjugation of two different therapeutic agents to branches of the same 3WJ nanoparticle for a combinational effect of PI3K/mTOR inhibitor and a chemotherapy agent would greatly enhance therapeutic effect and serve as a viable strategy to eliminate cancer cells." (PMID 40115434, 2024). "In addition, CD133+ cancer cells can modulate the mTOR pathway, which controls both FOXO3a activity and the autophagy programs." (PMID 39456981, 2024). "The most likely antiproliferative mechanism of metformin was reportedly associated with its ability to activate AMPK and LKB1, which inhibits the mechanistic target of rapamycin (mTOR) (a commonly dysregulated pathway in cancer) and consequently inhibit protein synthesis and cell proliferation." (PMID 39796103, 2024). "This may be due to the effects of PKMYT1 on enhancing the AKT/mTOR signaling pathway in promoting carcinogenesis and the progression of cancer cells through other pathways, such as activation of Notch signaling." (PMID 38291367, 2024). "mTOR signaling has frequently been affected in human cancers." (PMID 38539200, 2024). "Consequently, numerous mTOR inhibitors have been developed and employed clinically for cancer treatment." (PMID 38725843, 2024). "The mTOR pathway is pivotal in controlling cell survival, metabolism, growth, and protein synthesis, bridging both healthy and diseased states, particularly in the realm of cancer." (PMID 39595628, 2024). "Finally, given the variability of p62 and mTOR's role in different types of cancers, and their complex interplay with various growth factor signals, further investigation tailored toward specific treatment circumstances is required for mTOR-based therapy." (PMID 38560690, 2024). "Based on these findings, we believe that CLs may have beneficial effects on health as they potentially suppress EMT and CSCs, as well as the cancer-potentiating pathway of Akt/mTOR/c-Myc." (PMID 38672078, 2024). "As such, CH can compromise the normal working of PI3K/Akt and MAPK/ERK pathways (foremost therapeutic targets in cancer treatment) by suppressing mTOR expression, thus inhibiting autophagic thrust with simultaneous enhancement of apoptosis progression in cancer cells." (PMID 38966181, 2024). "In addition to the role of EGFR in cancer biology, the mechanistic target of rapamycin (mTOR) signaling is a major pathway that mediate a wide variety of cellular physiological processes, such as apoptosis, autophagy, amino acid metabolism, and proliferation." (PMID 38560690, 2024). "However, JPH203 prevents the radiation-induced amino acids uptake, increases the sensitivity of cancer cells to radiation, decreases mTOR activity, and promotes cells' senescence after irradiation." (PMID 38705513, 2024). "In synopsis, our findings suggest that 4EBP1 may represent a therapeutic target in metabolically challenged tumor types, while warranting caution on the use of mTOR inhibitors in these cancers." (PMID 38744825, 2024). "Moreover, MiR-155-5p regulates the PDK1/mTOR pathway to inhibit LC3 but promote P62 protein expression in cancer cells, thus it further influences cellular autophagy activity." (PMID 38577616, 2024). "Targeting PI3K/Akt/mTOR has been tested across almost all cancer types." (PMID 38319732, 2024).
cancer (continued). "The PI3K/AKT/mTOR signaling pathway is a prevalent mechanism of cancer activation, contributing to tumor cell proliferation and various malignant biological processes, as well as influencing the expression of genes related to cancer cell proliferation and apoptosis." (PMID 39399463, 2024). "Beyond these effects, DNA methylation also induces the silencing of key TSGs within metabolic signaling pathways such as phosphoinositide 3‐kinase (PI3K)/AKT/mammalian target of rapamycin (mTOR), which are crucial for the activation of glycolysis and the specialized metabolism of cancer cells." (PMID 38374872, 2024). "mTOR has been shown to frequently undergo aberrant activation in cancer." (PMID 38474373, 2024). "The mTOR pathway is involved in coordinating cellular senescence processes, and its inhibition by rapamycin or similar compounds has been shown to prevent cancer in various models." (PMID 39596005, 2024). "Compounds targeting these pathways may be active based on preclinical mechanistic cancer models and/or based on cancer patient data, including immune checkpoint blockade (anti-PD-1/PD-L1) and inhibitors of mTOR, PARP, ATR, EZH2, and HDAC." (PMID 39697230, 2024). "This assay showed high protein synthesis activity in control solvent-treated cells and strong inhibition of protein synthesis by MP1 and cycloheximide in both cell lines, suggesting the anti-cancer potential of MP1 is partly based on targeting the MYC/mTOR-driven protein synthesis pathway." (PMID 38200580, 2024). "Moreover, Rheb1 regulates many neuronal activities via mTOR, a protein well-known for being involved in cancer hallmarks." (PMID 38338768, 2024). "Furthermore, metabolites regulated by L. rhamnosus LRJ-1 are mainly enriched in KEGG pathways including mTOR signaling pathway, choline metabolism in cancer, GABAergic synapse, etc.." (PMID 39619641, 2024). "Consequently, mTOR is a significant and intriguing target for therapeutic intervention against cancer." (PMID 39519654, 2024). "The examination of the function of Mammalian Enhancer-of-Akt-1-7 (mEAK-7) in mTORC1 signaling reveals that S6K2 promotes cell proliferation and migration in response to mTOR activation in various cancer types, such as hepatocellular carcinoma and lymph node-positive breast cancers." (PMID 39796034, 2024). "Through anti-cancer therapy targeting CSCs by precisely regulating the mTOR pathway, the effectiveness of chemotherapy could be enhanced, potentially eliminating cancer metastasis and recurrence." (PMID 39349424, 2024). "Importantly, these genes are the key regulators of the mTOR pathway, which is potentially known to be deregulated in various cancers." (PMID 38576486, 2024). "The clinical scenario of the latent metastatic cell progression may become clear if one applies the accumulated knowledge about the mTOR signaling pattern in dormant cancer cells." (PMID 38418814, 2024). "Moreover, TCF7L1-mediated upregulation of HSPB6 leads to suppression of the PI3K/AKT/mTOR signaling pathway, a key driver of cancer progression." (PMID 39608715, 2024). "INK-128, a potent mTOR inhibitor, has shown encouraging potential in the treatment of cancer." (PMID 38322112, 2024). "In addition, silibinin inhibits hypoxia‐inducible factor‐1α through the mTOR–ribosomal protein S6 kinase–4E‐binding protein‐1 pathway in human cancer cells to induce autophagy." (PMID 38222315, 2024).
cancer (continued). "Targeting the mTOR signaling pathway in cancer therapy may have a strong therapeutic benefit, directly inhibiting tumor progression and simultaneously enhancing antitumor immune responses." (PMID 38791040, 2024). "Moreover, supplying cancer cells with albumin during treatment with an inhibitor of the mammalian target of rapamycin (mTOR) boosts albumin breakdown in lysosomes." (PMID 39353906, 2024). "These experiments demonstrate that targeting the E3 ligases that regulate key proteins in the PI3K/AKT/mTOR signaling pathway offers promising therapeutic avenues for various cancers, providing a new direction for developing more effective cancer treatment strategies." (PMID 39048965, 2024). "PI3K/Akt/mTOR signaling is one of the most critical intracellular signaling pathways controlling essential cellular functions, but key components of the pathway are frequently dysregulated in a variety of cancers." (PMID 38755125, 2024). "Under HDS conditions, cancer cells exhibit the capacity to adapt their growth signaling and metabolic states, potentially involving upregulation of the wingless/Wnt pathway and mTOR signaling, along with evasion of apoptosis and genome instability, which contributes to elevated mutation rates." (PMID 39261338, 2024). "Notably, genes that were downregulated predominantly clustered in cancer-related pathways, including Hippo, mTOR, and Wnt." (PMID 38613073, 2024). "The application of kinase inhibitors (KIs) in HNSCC, specifically mTOR and DNA-PK inhibitors, can increase radiosensitivity and therefore presents a promising strategy when used simultaneously with ionizing radiation (IR) in cancer treatment." (PMID 38391917, 2024). "Moreover, c-Myc is a downstream target of the Akt/mTOR pathway, and its expression has been linked to both the EMT process and stem cell-like properties in cancer." (PMID 38672078, 2024). "Loss of PTEN is frequently met in cancer, leading to PI3K/AKT/mTOR hyperactivation." (PMID 38339127, 2024). "Dysregulation and alterations in mTOR pathways lead to cancer development and advancement." (PMID 38532930, 2024). "mTOR regulates stem cell and cancer stem cell characteristics." (PMID 38474373, 2024). "mTOR in cancer is related to tumorigenesis, metastasis, tumor development and angiogenesis." (PMID 39349424, 2024). "Based on a recent study, FAS inhibitor cerulenin could inhibit the mTOR signaling pathway, and suppressed cancer cell proliferation and migration." (PMID 38495496, 2024). "Notably, the components in the newly identified AKT/mTOR/STAT3/ID1 axis play pivotal roles in cancer metastasis." (PMID 38183094, 2024). "Taken together, these findings underscore the therapeutic potential of mTOR inhibitors in diverse conditions, including cancer, immunosuppression post-organ transplantation, and AIDs, through their ability to modulate critical upstream and downstream signaling molecules." (PMID 39575238, 2024). "Additionally, some of the drugs used in therapies for cancer inhibit the proliferation of the tumor cells by the mTOR pathway." (PMID 38338233, 2024). "Hypoxia in the tumor micro‐environment leads to up‐regulation of lipid metabolism‐related genes, such as ACSS2, which enhances lipid metabolism reprogramming through pathways like HMGCS1 mediated PI3K/AKT/mTOR, promoting the progression of various cancers, including pNETs." (PMID 39524139, 2024). "In addition, cell line models have demonstrated that fibronectin can induce EMT through the p-AKT/p-mTOR pathway to promote cancer cell motility." (PMID 38496751, 2024). "To further confirm the relationship between ALDH and mTORC1 signaling, we determined whether mTOR activation could rescue the inhibitory effect of ALDH inhibitor on cancer cells." (PMID 39394200, 2024). "However, it turned out that after discontinuing the drug, the cancer process quickly recurs, prompting us to examine the safety endpoints of long-term pharmacotherapy with mTOR inhibitors." (PMID 39410026, 2024).